POLG (DNA polymerase gamma, catalytic subunit)
Description:
Catalytic subunit of DNA polymerase gamma solely responsible for replication of mitochondrial DNA (mtDNA). Replicates both heavy and light strands of the circular mtDNA genome using a single-stranded DNA template, RNA primers and the four deoxyribonucleoside triphosphates as substrates. Has 5' -> 3' polymerase activity. Functionally interacts with TWNK and SSBP1 at the replication fork to form a highly processive replisome, where TWNK unwinds the double-stranded DNA template prior to replication and SSBP1 covers the parental heavy strand to enable continuous replication of the entire mitochondrial genome. A single nucleotide incorporation cycle includes binding of the incoming nucleotide at the insertion site, a phosphodiester bond formation reaction that extends the 3'-end of the primer DNA, and translocation of the primer terminus to the post-insertion site. After completing replication of a mtDNA strand, mediates 3' -> 5' exonucleolytic degradation at the nick to enable proper ligation. Highly accurate due to high nucleotide selectivity and 3' -> 5' exonucleolytic proofreading. Proficiently corrects base substitutions, single-base additions and deletions in non-repetitive sequences and short repeats, but displays lower proofreading activity when replicating longer homopolymeric stretches. Exerts exonuclease activity toward single-stranded DNA and double-stranded DNA containing 3'-terminal mispairs. When a misincorporation occurs, transitions from replication to a pro-nucleolytic editing mode and removes the missincorporated nucleoside in the exonuclease active site. Proceeds via an SN2 nucleolytic mechanism in which Asp-198 catalyzes phosphodiester bond hydrolysis and Glu-200 stabilizes the leaving group. As a result the primer strand becomes one nucleotide shorter and is positioned in the post-insertion site, ready to resume DNA synthesis. Exerts 5'-deoxyribose phosphate (dRP) lyase activity and mediates repair-associated mtDNA synthesis (gap filling) in base-excision repair pathway. Catalyzes the release of the 5'-terminal 2-deoxyribose-5-phosphate sugar moiety from incised apurinic/apyrimidinic (AP) sites to produce a substrate for DNA ligase. The dRP lyase reaction does not require divalent metal ions and likely proceeds via a Schiff base intermediate in a beta-elimination reaction mechanism.
Synonyms: POLG1; POLGA; MIRAS; MTDPS4A; MTDPS4B; PEO; PolG-alpha; SANDO; SCAE
Tractability: Small molecule: a structure with a bound ligand is known; a high-quality ligand is known; it has a binding pocket of medium quality. PROTAC: ubiquitination databases record sites on it; its protein half-life has been measured; a small molecule that binds it is known.
Target class: Enzyme; Transferase
Safety:
Unwanted effects reported when the protein is acted on. In parentheses: how it was acted on, where the effect was seen, and who reports it.
hepatotoxicity (source: ClinPGx)
Gene: Protein-coding gene on chromosome 15 (89,305,198 to 89,334,861, reverse strand). Ensembl gene ENSG00000140521.
Subcellular location: Mitochondrion; Mitochondrion matrix, mitochondrion nucleoid
Subcellular location (Human Protein Atlas): Mitochondria
Pathways (Reactome):
DNA Replication: Strand-asynchronous mitochondrial DNA replication
Gene Ontology:
Molecular function: 3'-5' exonuclease activity; 5'-deoxyribose-5-phosphate lyase activity; chromatin binding; DNA binding; DNA polymerase activity; DNA-directed DNA polymerase activity; protease binding; protein binding; single-stranded DNA 3'-5' DNA exonuclease activity
Biological process: base-excision repair; base-excision repair, gap-filling; DNA replication proofreading; DNA-templated DNA replication; mitochondrial DNA replication; DNA metabolic process; DNA biosynthetic process; DNA replication
Cellular component: gamma DNA polymerase complex; mitochondrial chromosome; mitochondrial matrix; mitochondrial nucleoid; mitochondrion; protein-containing complex; chromosome
Genetic constraint (gnomAD): Loss-of-function variants: 109 observed, 150.96 expected, observed/expected ratio (o/e) 0.72, 90% interval 0.62 to 0.85. The upper end of that interval is the gene's LOEUF score, 0.85, which puts it in group 3 of 6, group 1 being the genes least tolerant of losing a copy. Missense variants: 1,680 observed, 1,631.8 expected, observed/expected ratio (o/e) 1.03, 90% interval 0.99 to 1.07. Synonymous variants: 701 observed, 624.57 expected, observed/expected ratio (o/e) 1.12, 90% interval 1.05 to 1.2.
Gene-disease validity (ClinGen):
ClinGen rates the evidence that POLG causes each of these diseases.
Leigh syndrome (autosomal recessive): Limited. A progressive neurological disease defined by specific neuropathological features associating brainstem and basal ganglia lesions.
Homologues: Orthologues: chimpanzee POLG (99% identical), macaque POLG (96% identical), pig POLG (89% identical), rabbit POLG (89% identical), dog POLG (87% identical), mouse Polg (87% identical), guinea pig POLG (86% identical), rat Polg (86% identical), zebrafish polg (65% identical), tropical clawed frog polg (64% identical), Drosophila melanogaster PolG1 (42% identical), Caenorhabditis elegans polg-1 (29% identical).
Diseases named in the same sentence as POLG in open-access papers:
POLG is named in the same sentence as 264 diseases in open-access papers, as found by Europe PMC text mining. Sharing a sentence is not in itself a finding about the gene and the disease. The quoted sentences say what the papers report.
Ataxia (57 papers, 2010 to 2026). Ataxia refers to impaired coordination of voluntary muscle movement. "Early-onset diseases associated with POLG mutations such as Alpers–Huttenlocher syndrome cause depletion of mtDNA, whereas the adult-onset diseases such as ataxia and PEO are associated with multiple mtDNA deletions." (PMID 41226312, 2025). "Most POLG mutations are linked to autosomal recessive progressive external ophthalmoplegia (arPEO), ataxia, or Alpers syndrome, and are frequently observed as compound heterozygous recessive variants." (PMID 41226312, 2025). "POLG mutations seem to be a frequent cause of cerebellar ataxia, accounting for up to 11% of cases in whom repeat expansion diseases have been excluded, as reported in a large German cohort." (PMID 41245005, 2025). "Cerebellar ataxia is one of the most common movement disorders in mitochondrial disease, with POLG mutations being a frequent cause." (PMID 41245005, 2025). "In this scoping review, we summarized data from studies, mainly case reports or case series, describing patients with cerebellar ataxia due to POLG mutations." (PMID 41245005, 2025). "This scoping review aimed to summarize current knowledge regarding cerebellar ataxia due to POLG mutations, focusing on epidemiological, clinical, radiological features and genotype-phenotype correlations." (PMID 41245005, 2025). "In this scoping review, we summarize current knowledge regarding cerebellar ataxia due to POLG mutations, focusing on epidemiological, clinical, radiological features and genotype-phenotype correlations." (PMID 41245005, 2025). "Cerebellar ataxia due to POLG mutations presented in combination with other neurological and non-neurological symptoms." (PMID 41245005, 2025). "POLG mutations are associated with a variety of manifestations, in children in particular by Alpers–Huttenlocher disease or, later, by spinocerebellar ataxia and epilepsy." (PMID 40149709, 2025). "In homozygous or compound heterozygous POLG mutation carriers, cerebellar ataxia seems to be progressive, and can initiate from either the bulbar muscles, trunk, or limbs." (PMID 41245005, 2025). "Other movement disorders, such as myoclonus, tremor, dystonia (focal or segmental), and chorea, in descending order, can accompany cerebellar ataxia due to a POLG mutation." (PMID 41245005, 2025). "The most common variants in POLG-related cerebellar ataxia are W748S and A476T, localized in the linker region of POLG gene." (PMID 41245005, 2025). "The latency of developing cerebellar ataxia in patients with POLG mutations varied significantly, from being the presenting symptom up to 40 years after disease onset (mean 2.9 ± 6.5 years)." (PMID 41245005, 2025). "In the statistical descriptive analysis, only the patients having cerebellar ataxia due to POLG mutations were included." (PMID 41245005, 2025). "The observed speech timing deficits are similar to those observed in other genetic ataxias such as SCA2, FRDA, POLG-associated ataxia, and ARSCACS." (PMID 36633828, 2024). "Ataxia in POLG-related disease can be sensory or cerebellar and it seems to be a frequent cause of ataxia in Central Europe once repeat expansion diseases had been excluded." (PMID 37648940, 2023). "POLG mutations cause a wide spectrum of overlapping phenotypes including ataxia, seizures, myopathy, progressive external ophthalmoplegia, as well as several movement disorders." (PMID 37648940, 2023). "Mutations in POLG are often found in mitochondrial diseases, such as ataxia, progressive external ophthalmoplegia, mitochondrial epilepsy, Alpers’ syndrome, Leigh’s syndrome, Parkinsonism, and male infertility." (PMID 36833361, 2023). "Parkinsonism should be carefully investigated, especially why in some disorders or specific genotype (e.g. SCAs, POLG-related ataxias, some PSEN1 mutations, SPG7) a good levodopa response has been reported." (PMID 37648940, 2023).
Ataxia (continued). "POLG mutations are usually studied in mitochondrial diseases, including ataxia, progressive external ophthalmoplegia, mitochondrial epilepsy, Alpers’ syndrome, Leigh’s syndrome, Parkinsonism, and male infertility." (PMID 36833361, 2023). "Ataxia was mostly cerebellar or spinocerebellar; pure sensory ataxia was found in 16% of ataxic patients, mainly in POLG pathogenic variants in the setting of a SANDO phenotype." (PMID 34259909, 2022). "POLG mutations are the most common cause of mitochondrial disease, particularly mitochondrial epilepsy, polyneuropathy, ataxia, and PEO." (PMID 36157077, 2022). "FA is considered the commonest recessively inherited spinocerebellar ataxia, although in Finland and Norway, mutations in POLG, which can give a similar phenotype (IOSCA), are more common." (PMID 35203288, 2022). "Homozygous POLG mutation c.2243G > C (p.Trp748Ser) identified in two patients with m.3243A > G (P6 and P7) was previously reported in ataxia patients of European origin." (PMID 33484326, 2021). "In line with this, mtDNA heteroplasmy associated with complex I deficiency was found in cerebellar Purkinje cells of mitochondrial disease patients suffering from ataxia, including patients with POLG mutations, supporting a cerebellar involvement in ataxias." (PMID 34295920, 2021). "Expansion in ATXN8/OS results in the majority of dominant ataxias in Finland, while mutations in RFC1 and POLG are the most common cause of recessive ataxias." (PMID 34600502, 2021). "The majority of our patients with nuclear gene mutations were adults with POLG mutations and phenotypes consisting of epilepsy, neuropathy and/or ataxia." (PMID 33501425, 2021). "As for POLG-related disease, it is caused by POLG defect and related to Alpers-Hüttenlocher syndrome or to adult-onset encephalopathy, spinocerebellar ataxia, and epilepsy." (PMID 33363507, 2020). "The clinical diseases caused by POLG mutations are enormously variable in severity, ranging from mild ataxia and chronic PEO to severe Alpers disease, but with some phenotype–genotype correlation." (PMID 23448099, 2013). "The p.W748S mutation was shown to be common in POLG-related ataxias in European populations." (PMID 41245005, 2025). "This review summarizes current knowledge regarding cerebellar ataxia due to POLG mutations." (PMID 41245005, 2025). "Cerebellar ataxia due to POLG mutations can present in combination with progressive external ophthalmoplegia, sensory neuropathy, epilepsy (including status epilepticus), headache, other hyperkinetic movement disorders such as myoclonus and tremor, cognitive or affective disorders." (PMID 41245005, 2025). "Mutations in the mitochondrial DNA polymerase subunit gamma “POLG”, responsible for the replication and repair of mitochondrial DNA, are increasing recognized causes of ataxia and peripheral neuropathy, variably associated to cerebellar or extracerebellar oculomotor changes." (PMID 38390227, 2023). "Ataxia was associated with both POLG and m.8344A > G pathogenic variants." (PMID 34259909, 2022). "Adult-onset PEO associated with POLG mutations are frequently complicated by neurological symptoms, including spinocerebellar ataxia, peripheral motor neuropathy, extrapyramidal signs (parkinsonism), and psychiatric abnormality (unipolar or bipolar affective disorder)." (PMID 35203288, 2022). "Ataxia is a prominent clinical feature among mitochondrial diseases related to mutated POLG." (PMID 34295920, 2021). "Mutations in POLG may cause variable clinical manifestations, including parkinsonism, epilepsy, cerebellar ataxia, neuropathy, and progressive external ophthalmoplegia." (PMID 30941926, 2019). "In POLG mutation carriers, cerebellar ataxia is often progressive and can start either from bulbar muscles, with dysarthria and dysphonia as presenting symptoms, from the trunk, presenting as gait imbalance, or from the limbs, presenting as symmetrical or asymmetrical limb ataxia." (PMID 41245005, 2025).
Ataxia (continued). "CACNA1A variants have been reported in patients with episodic ataxia and spinocerebellar ataxia; however, in this patient, the initial targeted diagnostic screens prior to ES had focused on respiratory chain defects and common mitochondrial mutation analysis (including m.3243A>G, m.8993 T>C, POLG)." (PMID 31345272, 2019). "On the other hand, pyramidal tract signs, square wave jerks, and pes cavus will suggest Friedreich’s ataxia, although the latter has been reported in individual cases of POLG-related ataxia as well." (PMID 41245005, 2025). "The present analysis suffers from some limitations, including the underreported or missing data in the included studies, regarding epidemiological, clinical, laboratory, or outcome measures of patients with POLG-related ataxia." (PMID 41245005, 2025). "As the age of ataxia onset varies greatly, both pediatric and adult neurologists should be able to suspect POLG-related ataxia." (PMID 41245005, 2025). "In terms of progression, the progression rate of POLG-related ataxia seems to be faster than Friedreich’s and SCA type 6 but slower than SCA 1, 2, 3, and multiple system atrophy (MSA)." (PMID 41245005, 2025). "In this patient cohort, 19 of 28 patients displayed clinical signs of ataxia, including 7 patients with Alpers’ syndrome and 12 adult patients with POLG and mtDNA PMD." (PMID 40445405, 2025). "Neuroimaging features in POLG-related ataxia, as reported in most reviewed studies, include cerebellar atrophy, which is usually mild or moderate." (PMID 41245005, 2025). "We searched PubMed and Web of Science databases for all articles published in English till September 2025 describing cases of POLG-related cerebellar ataxia." (PMID 41245005, 2025). "Demographics and common clinical findings of patients with POLG-related cerebellar ataxia (N = 184)." (PMID 41245005, 2025). "Similar to POLG-related disease, the clinical spectrum of heterozygous POLG2 mutations comprises cerebellar ataxia and PEO in adulthood-onset and metabolic abnormalities and seizures in childhood-onset cases." (PMID 37085601, 2024). "POLG mutations result in mitochondrial DNA depletion and/or multiple deletions and are responsible of different phenotypes including POLG related ataxia-neuropathy disorders (SANDO/MIRAS/arPEO plus)." (PMID 38390227, 2023). "Expansion in ATXN8/OS (SCA8) was the most common cause of dominantly inherited ataxia, while the homozygous p.Trp748Ser mutation in POLG and the biallelic expansion in RFC1 were the most common causes of recessively inherited ataxia." (PMID 34600502, 2021). "This feature would be very interesting since POLG mutations are associated with 10–25% of progressive external ophthalmoplegia (PEO) and >10% of ataxia cases and are the most common cause of mitochondrial epilepsy." (PMID 34830106, 2021). "We found that mutations in ATXN8/OS, POLG and RFC1 are the most common genetic causes of ataxia in Finland." (PMID 34600502, 2021). "Childhood or teenage onset should raise the suspicion for Friedreich ataxia, ataxia with oculomotor apraxia 1 and 2, and POLG-related disorders." (PMID 31267374, 2019). "Imaging findings of cerebellar atrophy, which is not a feature of Friedreich’s ataxia, in combination with signal changes in cerebellar hemispheres, thalami, (inferior) olivary nuclei, and, less commonly, cortical signal changes, will speak for POLG-related ataxia." (PMID 41245005, 2025). "POLG-related ataxia shares some common features with Friedreich’s ataxia, such as ataxia with both cerebellar and sensory components, areflexia, impaired vibration sense (in the context of axonal sensory neuropathy), diabetes, and age of onset commonly <40 years." (PMID 41245005, 2025). "A genetic screening for ataxia covering nearly 50 genes (next generation sequencing panel) ruled out pathogenic mutations associated with spinocerebellar ataxia (SCA) as well as familial PAPT forms (POLG, GFAP, and SPG7)." (PMID 39450592, 2025).